EGFR (epidermal growth factor receptor)
Diseases named in the same sentence as EGFR in open-access papers (continued):
Sharing a sentence is not in itself a finding about the gene and the disease.
colorectal cancer (continued). "Subsequently, FOXK2 activates the transcription of EGFR and ZEB1, crucial regulators of the epithelial-mesenchymal transition (EMT), invasion, and metastasis in colorectal cancer." (PMID 38741782, 2024). "For instance, simultaneous inhibition of EGFR and KRASG12C is necessary in colorectal cancer to overcome resistance to KRASG12C blockade." (PMID 38706597, 2024). "In colorectal cancer, OGN reversed epithelial to mesenchymal transition (EMT) and invasive ability by the EGFR/Akt signaling." (PMID 38402185, 2024). "A phase I clinical trial (NCT03618381) is currently evaluating the safety and efficacy of EGFR-targeting CAR-T cells in patients with advanced solid tumors, including colorectal cancer." (PMID 39417449, 2024). "Likewise, CTCs were enumerated in RAS-BRAF wild-type colorectal cancer patients receiving third-line anti-EGFR monoclonal antibodies, cetuximab or panitumumab and found that CTC status assessed early on during targeted therapy may predict treatment failure in advance compared to imaging-based tools." (PMID 38398206, 2024). "This aberration in EGFR signaling pathways provides a crucial window of opportunity for disease control, making EGFR antibodies a cornerstone in the standard therapy for colorectal carcinoma (CRC) patients." (PMID 38844562, 2024). "While BRAF inhibitor combinations with EGFR and/or MEK inhibitors have improved clinical efficacy in BRAFV600E colorectal cancer (CRC), response rates remain low and lack durability." (PMID 36702949, 2023). "In colorectal cancer (CRC), it has been demonstrated that there exists a connection between elevated levels of EGFR expression and the invasion of tumors." (PMID 37895912, 2023). "This approach has also been successfully applied to discover novel synthetic lethal interactions with the RAS oncogene in colorectal cancer cells and to identify dependency between NfκB, FAS and EGFR pathways in lung cancer." (PMID 37202533, 2023). "In colorectal cancer, OGN upregulation has been found to induce EGFR endocytosis and inhibit EMT through the EGFR/Akt pathway." (PMID 36980828, 2023). "Because somatic mutations in KRAS are linked to poor response to anti-epidermal growth factor receptor (EGFR) focused therapy, KRAS is a predictive biomarker for colorectal cancer." (PMID 36950511, 2023). "TNNT2 can upregulate EGFR and HER2-related proteins in colorectal cancer cells and promote the occurrence of EMT." (PMID 37481519, 2023). "This study reveals that TNNT2 can promote the invasion and metastasis of colorectal cancer through EGFR/HER2/EMT signal axis, and reveals the potential of TNNT2 as a therapeutic target for colorectal cancer." (PMID 37481519, 2023). "Guided by various clinical trials for colorectal cancer, we selected and tested combinations of BRAF/EGFR, BRAF/MEK, MEK/WNT, and BRAF/WNT inhibitors at their IC50 concentrations against CRC2 spheroids." (PMID 37791907, 2023). "With the introduction of cetuximab and panitumumab, two anti-epidermal growth factor receptor (EGFR)-targeted antibodies, the treatment of progressive colorectal cancer has entered the era of customized therapy." (PMID 37760468, 2023). "We retrospectively evaluated patients with unresectable advanced or recurrent colorectal cancer who were treated with a cytotoxic anticancer drug and a VEGF or EGFR inhibitor combination between April 2016 and October 2021." (PMID 37394446, 2023). "It has been reported that EGFR is involved in regulating EMT in prostate cancer cells, pancreatic cancer cells, and colorectal cancer cells." (PMID 36841821, 2023). "In colorectal cancer, combined BRAF, EGFR, and MEK inhibition in patients resulted in modest improvement in response rates." (PMID 37917191, 2023). "Cetuximab, a chimeric anti-EGFR monoclonal antibody, has been approved by the FDA as an EGFR inhibitor for the treatment of colorectal cancer and head and neck cancer." (PMID 36902321, 2023).
colorectal cancer (continued). "At high concentrations (612 μM), 56 induced cell death in K‐RAS‐mutant HCT116 colorectal cancer cells (CRC) when combined with cetuximab (25 μg/ml), a monoclonal antibody against epidermal growth factor receptor (EGFR)." (PMID 36658724, 2023). "ciRS-7, a potential miR-7 sponge, enhanced EGFR and CRAF activation, leading to a more aggressive colorectal cancer phenotype." (PMID 38111008, 2023). "In colorectal cancer KRAS (including Raf/Ras/MEK/Erk), EGFR, c-Met, Apo2L, FAK, NF-κB are plausible molecule targets." (PMID 36966394, 2023). "Colorectal cancer treatment has been shaped by targeting the vascular endothelial growth factor (VEGF) and EGFR." (PMID 37686423, 2023). "As recently reported, CHRM3 and post-M3R signaling activation promote cell proliferation via the EGFR/ERK and MAPK pathways in colorectal cancer." (PMID 37744266, 2023). "Taken together, we show that pKAL enhances the anticancer effect of β-Lap in HCT116-OxPt-R colorectal cancer cells through the modulation of TERT, CD44, and EGFR-mediated multiple signaling networks." (PMID 38139333, 2023). "BRAF-mutant colorectal cancer is more prone to acquired resistance than BRAF-mutant melanoma, although CRAF was activated by oncogenic EGFR signaling in the former." (PMID 38111008, 2023). "MiR-4689 has been reported to effectively inhibit Kirsten rat sarcoma virus (KRAS)-driven epidermal growth factor receptor (EGFR) signaling by directly inhibiting KRAS and AKT1 in colorectal cancer cells." (PMID 37858140, 2023). "Taken together, our results show that pKAL enhances the anticancer effect of β-Lap in HCT116 colorectal cancer cells containing OxPt-R by downregulating TERT, CD44, EGFR, and upregulated oxaliplatin resistance-related proteins." (PMID 38139333, 2023). "However, several retrospective randomized studies provided evidence indicating that administering mAbs-targeting EGFR, such as cetuximab, does not provide any benefits to patients with advanced colorectal cancer with tumors containing activating mutations in the KRAS and other RAS family genes." (PMID 38201251, 2023). "Tri-specific TCEs targeting CD3, epidermal growth factor receptor (EGFR), and epithelial cellular adhesion molecule (EpCAM) were developed to specifically kill EGFR and/or EpCAM-expressing colorectal cancer cells." (PMID 36971134, 2023). "Prior to treatment with NEO-201, ten and six patients with colorectal cancer had received anti-VEGF and anti-EGFR directed therapy respectively, and one patient had previously received an immune checkpoint inhibitor (pembrolizumab)." (PMID 36991390, 2023). "Increasing evidence has demonstrated that EGFR-TKIs are a radiation sensitizer in the treatment of NSCLC, head and neck, breast, and colorectal cancers." (PMID 36765577, 2023). "TGF-α, as the EGFR ligand, was found to be overexpressed through the EGFR-MET interaction and ultimately contributed to cetuximab resistance in colorectal cancer cells." (PMID 38269272, 2023). "Statistically, REG4 expression was significantly lower in colorectal cancer than in normal mucosa or adenomas, and inversely correlated with poor differentiation, venous invasion, low expression of MUC2 and EGFR phosphorylated at Tyr1068." (PMID 36172286, 2022). "Anti-EGFR antibodies, such as cetuximab and panitumumab, are effective therapies and have already been approved by the FDA as first-line therapy for colorectal cancer." (PMID 35453596, 2022). "The chimeric anti-EGFR mAb, Cetuximab, has been approved by the U.S FDA and used to treat head and neck cancer and colorectal cancer." (PMID 35052809, 2022). "In colorectal cancers (CRCs), adaptive resistance emerges against BRAFi through the activation of MAPK signaling by upstream regulator EGFR." (PMID 35725577, 2022).
colorectal cancer (continued). "Results from colony formation, wound healing assay and transwell invasion tests consistently demonstrated that EGFR overexpression completely blocked CB1-activation-induced suppression in cell proliferation, migration and invasion in colorectal cancer cells." (PMID 35641479, 2022). "However, as anti-EGFR antibody treatment induces ADCP of human colorectal cancer cells by macrophages, independent of mutations in EGFR signaling pathways, mutations in KRAS or BRAF are not expected to negatively impact the efficacy of preoperative antibody treatment to eliminate CTCs." (PMID 35035479, 2022). "AF8c, a lapatinib hybrid quinazoline-based EGFR/HER2 inhibitor, was chosen to scrutinize its antiproliferative activity in colorectal cancer (CRC) cells." (PMID 35804815, 2022). "To this end, we have previously obtained a stable complex comprised of the internalizing anti-EGFR-antibody cetuximab bound to cationic protamine and the anionic siRNA against KRAS and PIK3CA that specifically enters colorectal cancer cells." (PMID 36457063, 2022). "COLO320DM is an EGFR-negative human colorectal cancer cell line with wild-type KRAS/BRAF, which is an ideal cell model for generating stable EGFR mutant cell lines." (PMID 35907884, 2022). "Our aim was to define the expression of HER2 in colorectal cancer stem cells (CR-CSCs) and its possible role as therapeutic target in CRC resistant to anti- epidermal growth factor receptor (EGFR) therapy." (PMID 33436496, 2022). "It has been previously shown that GRd inhibits epidermal growth factor receptor (EGFR) signalling and suppresses cancer stem cell−like properties in colorectal cancer (CRC) cells, which result in the reduction of CRC metastasis." (PMID 36127129, 2022). "SEC11A can promote the phosphorylation of epidermal growth factor receptor (EGFR) and the downstream extracellular signal-regulated kinase (ERK) and protein kinase B (Akt) in colorectal cancer cells." (PMID 35653344, 2022). "Currently, the anti-EGFR mAbs cetuximab and panitumumab are used in the treatment of metastatic KRAS wild-type colorectal cancer patients." (PMID 35035479, 2022). "Epidermal growth factor receptor (EGFR), a 170-kDa transmembrane glycoprotein composed of an intracellular tyrosine-kinase domain, is one of the anticancer drug targets for colorectal cancer." (PMID 34991461, 2022). "The aim of this study was to investigate the expression of EGFR, HER2, and HER3 between primary and lymph node metastatic lesions of colorectal cancer." (PMID 35902718, 2022). "Epidermal growth factor receptor (EGFR) inhibitors, including cetuximab and panitumumab, are valuable therapeutics for colorectal cancer (CRC), but resistance to these inhibitors is common." (PMID 35650607, 2022). "We apply our novel scoring approaches to resections from a cohort of 34 colorectal cancer patients that have been stained by immunohistochemistry for HER2, CMET, CD44, and EGFR." (PMID 36601480, 2022). "Phase 1b recruited EGFR-positive patients with refractory advanced squamous cell carcinomas of the head and neck (SCCHN), nasopharyngeal carcinoma (NPC), and colorectal cancer (CRC)." (PMID 35511148, 2022). "To further confirm the effect of CB1 on EGFR mediated macrophage polarization, we knocked down EFGR and co-treated with AM251 in colorectal cancer cells." (PMID 35641479, 2022). "Most driver genes were only found in single cancer types and represented key disease-specific drivers such as EGFR and TERT in glioma, MYC in BNHL, and APC in colorectal cancer." (PMID 35947558, 2022). "Three NSCLC cell lines, A549, H1650, and H1975, and one colorectal cancer cell line, SW620 (with different EGFR and CXCR4 expression) were chosen for comparison." (PMID 35269297, 2022). "Therefore, NIR-PIT utilizing the anti-EGFR antibody might be successful in colorectal cancer." (PMID 35453596, 2022).
colorectal cancer (continued). "Moderate correlation rates in EGFR, HER2, and HER3 expression were observed between primary and metastatic lesions of colorectal cancer." (PMID 35902718, 2022). "The colorectal carcinoma cell lines Caco2, HCT116, HT29, and SW948 had similar EGFR expression, ranging from 20,000 to 40,000 molecules per cell." (PMID 35035479, 2022). "In colorectal carcinoma (CRC), TRIP13 interacted with the receptor tyrosine kinase fibroblast growth factor receptor 4 (FGFR4) and activated the epidermal growth factor receptor (EGFR)/AKT pathway to induce EMT." (PMID 36268276, 2022). "The epidermal growth factor receptor (EGFR) signaling plays a relevant role in the pathogenesis and progression of colorectal carcinoma (CRC)." (PMID 35205799, 2022). "To determine how EGFR and Akt affect the induction of anoikis in HCT116 colorectal cancer cells by SAE, we treated the cells with 20 μM EGFR inhibitor and 20 μM Akt inhibitor (gefitinib and LY294002) with or without SAE (100 μg/mL) for 24 h." (PMID 34094906, 2021). "We found that phospho-EGFR was significantly impaired, whereas the total EGFR was unchanged, suggesting that PRMT5 regulates EGFR activation in colorectal cancer." (PMID 33495409, 2021). "For colorectal cancer module, the analysis revealed the occurrence of approved drug targets TYMS, TOP1, BRAF and EGFR." (PMID 35053185, 2021). "EGFR and Akt were found to affect the growth and proliferation of HCT116 colorectal cancer cells, and SAE was also found to exhibit inhibitory effects on proliferation, similar to the inhibitors." (PMID 34094906, 2021). "Some of the anti-EGFR mAbs including cetuximab and panitumumab have been approved by FDA as first-line treatments of colorectal cancer." (PMID 36405499, 2021). "In colorectal cancer, the activation of epidermal growth factor receptors (EGF-R) included the processing of membrane-bound EGF-R which induced by ADAM17." (PMID 34182543, 2021). "Cetuximab is a recombinant mouse/human chimeric monoclonal antibody that targets EGFR to treat patients with EGFR- and wild-type Kirsten rat sarcoma 2 viral oncogene homolog (KRAS)-expressing colorectal cancer." (PMID 33802964, 2021). "Epidermal Growth Factor Receptor (EGFR) inhibitors are effective in the subset of RAS (KRAS, NRAS) wild-type colorectal cancer (CRC) patients." (PMID 34771559, 2021). "In particular, the epidermal growth factor receptor (EGFR) is known to be overexpressed in a variety of human cancer cell lines including pancreatic, breast, and colorectal cancers, and thus is an ideal marker for targeted tumor therapy." (PMID 33924180, 2021). "Our findings also pose the possibility that PRMT5 promotes colorectal cancer cell growth, cell cycle progression, and EMT via EGFR/Akt/GSK3β signaling axis." (PMID 33495409, 2021). "To address this clinical question, we evaluated the correlation between clinical outcome on anti‐EGFR treatment and tumor CD73 expression using a publicly available dataset of 70 cetuximab‐treated colorectal cancer patients (GSE5851)." (PMID 34165921, 2021). "Increased RHOU expression was detected in the EGFR PC9-CR cells, while the well-known oncogene in lung and colorectal cancer TLE4 was also induced by cisplatin in the PC9-CR cells." (PMID 34065402, 2021). "Cetuximab is an anti-epidermal growth-factor receptor (EGFR) monoclonal antibody approved for the treatment of squamous cell head and neck and RAS wild-type colorectal cancer." (PMID 33235314, 2021). "According to COSMIC, EGFR and MYC, the copy number gain rate in large intestine cancer is 3.48% and 7.8%, respectively, which is higher than the frequency of CNVs identified in the validation set of this study." (PMID 34680263, 2021). "Cetuximab, anti-EGFR monoclonal antibody, treatment reduced the number of CD206+ F4/80+ TAMs in AOM/DSS-induced colorectal cancer mouse model." (PMID 34209679, 2021).
colorectal cancer (continued). "Colorectal cancer patients with high expression levels of EGFR have poor prognoses and NSCLC patients with EGFR-positive expression had a higher incidence of brain metastases." (PMID 34830108, 2021). "Whereas for colorectal cancer (CRC) patient-derived CTCs, epidermal growth factor receptors (EGFR) were additionally stained to observe their expression (Patient 8 as representative)." (PMID 34641562, 2021). "EGR1 high expression correlates with resistance to anti-EGFR treatment in metastatic colorectal cancer patients treated with cetuximab, and silencing EGR1 expression promotes killing HCT116 colorectal cancer cells and delaying tumor growth." (PMID 33506057, 2021). "Nonetheless, we provide evidence to show that SMARCA4 promotes colorectal cancer cell proliferation by interacting with PRMT1 to activate TNS4 and EGFR transcription." (PMID 33853662, 2021). "The anti-epidermal growth factor receptor (EGFR) antibody introduces adaptable variations to the transcriptome and triggers tumor immune infiltration, resulting in colorectal cancer (CRC) treatment resistance." (PMID 33632198, 2021). "The role of EGFR and RARA in 5-fluorouracil (5-FU) resistant COAD (colorectal cancer) cells was analyzed." (PMID 31896739, 2020). "In other study, the supplementation of pomegranate extract in patients with colorectal cancer had a significant down-regulating effect on the expression of colorectal cancer-related genes such as CD44, CTNNB1, CDKN1A, and EGFR in surgical colon samples." (PMID 33322700, 2020). "The epidermal growth factor receptor (EGFR), usually overexpressed in colorectal cancer (CRC), plays a pivotal role in tumor growth and progression." (PMID 32796636, 2020). "In a subset of advanced colorectal cancers (CRCs), treatment of RAS wild-type (wt) tumors with the anti-EGFR antibodies cetuximab or panitumumab leads to the killing of drug-sensitive cells and tumor volume reduction." (PMID 32183295, 2020). "Hyperactivation of the EGFR/MAPK signalling pathway often promotes occurrence and metastasis of hepatocellular carcinoma, and colorectal cancer." (PMID 33304472, 2020). "Cetuximab (Erbitux®), a mouse/human chimeric antibody targeting anti-epidermal growth factor receptor (EGFR), received FDA approval for treating wild-type KRAS and EGFR-positive colorectal cancers." (PMID 32138170, 2020). "The specific mechanism is the binding of EGF to EGFR, which activates downstream signaling pathways, leading to the downregulation of E-cadherin and upregulation of vimentin, thereby inducing EMT in colorectal cancer cells." (PMID 32148496, 2020). "Anti-EGFR mAbs including panitumumab, cetuximab and nimotuzumab were approved for treatment of NSCLC and colorectal cancer." (PMID 33023595, 2020). "As for lung, breast and colorectal cancer, even in oral squamous cell carcinoma (OSCC) EGFR activation plays an important role in cancer progression and correlates with poor prognosis." (PMID 32517369, 2020). "In colorectal cancer, CD73 downregulated cell growth via EGFR and the β-catenin/cyclin D1 signalling pathway." (PMID 33187081, 2020). "The epidermal growth factor receptor (EGFR), through the MAP kinase and PI3K-Akt-mTOR axis, plays a pivotal role in colorectal cancer (CRC) pathogenesis." (PMID 33233823, 2020). "Real time PCR was used to assess the expression levels of EGFR, HER-2 and PTGS-2 genes, as onco-markers in colorectal cancer." (PMID 32401801, 2020). "This study demonstrated that EGF/EGFR can phosphorylate FAK and induce EMT in colorectal cancer cells." (PMID 32148496, 2020). "Among the EGFR inhibitors, monoclonal antibodies cetuximab and panitumumab have already been approved for treatment of RAS/RAF wild-type colorectal cancer." (PMID 32708005, 2020). "Thus, patients with colorectal cancer may be treated with other drugs, such as EGFR inhibitors." (PMID 32476297, 2020).